DRD2 (dopamine receptor D2)
Diseases named in the same sentence as DRD2 in open-access papers (continued):
Sharing a sentence is not in itself a finding about the gene and the disease.
schizophrenia (continued). "Penfluridol, a diphenylbutylpiperidine antipsychotic drug, has a longer elimination half-life than thioridazine, trifluoperazine, and pimozide when used to treat schizophrenia via targeting DRD2." (PMID 35461314, 2022). "In this paper, we found a high expression of DA receptor D2 (DRD2) and a significant consistency between HERV-W ENV and DRD2 in schizophrenia patients." (PMID 35062349, 2022). "Our findings demonstrate that HERV-W ENV triggered the hyperactive dopaminergic system via the DRD2/PP2A/AKT1/GSK3 cascade in schizophrenia." (PMID 35062349, 2022). "Depth analyses showed that there was a marked consistency between HERV-W ENV and DRD2 in schizophrenia." (PMID 35062349, 2022). "As with DA, the expression of DRD2 was also significantly higher in schizophrenia patients than in controls (p < 0.001 after outlier removal)." (PMID 35062349, 2022). "Our clinical results showed a significant positive correlation and a robust consistency between HERV-W ENV and DRD2 in schizophrenia patients." (PMID 35062349, 2022). "The mechanism of penfluridol against schizophrenia is thought to be blockade of DRs, especially DRD2." (PMID 35461314, 2022). "Our studies reported a robust increase in DA, DRD2, and HERV-W ENV in schizophrenia and displayed a positive correlation and marked consistency between DRD2 and HERV-W ENV." (PMID 35062349, 2022). "There have been numerous studies on DRD2 mRNA levels in schizophrenia, but the results are inconsistent." (PMID 35062349, 2022). "Here, we found that the concentration of DA and the expression of DA receptor D2 (DRD2) were significantly higher in schizophrenia patients than in healthy individuals." (PMID 35062349, 2022). "The rate was as high as 70.18%, indicating a marked consistency between HERV-W ENV and DRD2 expressions in the schizophrenia group." (PMID 35062349, 2022). "We also identified expression changes in key genes previously associated with schizophrenia such as ZNF804A and DRD2, indicating that AS3MT is a key regulator of both these genes." (PMID 35719055, 2022). "Linear regression indicated a visual representation of the robust correlation between HERV-W ENV and DRD2 (R2 = 0.9410) in schizophrenia patients." (PMID 35062349, 2022). "Long-term antagonism of DRD2 with antipsychotic drugs significantly increases metabolic side effects including weight gain and disturbed lipid metabolism in patients with schizophrenia." (PMID 33557912, 2021). "These hypomethylated genes in schizophrenia participants include dopamine receptor D2 (DRD2), DRD4 and dopamine receptor d6 (DRD6)." (PMID 34831111, 2021). "Its main indication is schizophrenia treatment, antagonizing mainly the DRD2 and also calcium channels." (PMID 34944601, 2021). "Most notably, mutations in both DRD2 and ATP2A2 have been identified by GWAS as common risk variants in schizophrenia." (PMID 34955759, 2021). "The only positive result was the observation that DRD2 rs6276 was significantly more frequent in patients with family history of schizophrenia." (PMID 32565876, 2020). "DRD2 mutant animals show adult onset of behaviors reminiscent of schizophrenia and endophenotypes at molecular, cellular, and physiological levels similar to those described from patients studies." (PMID 32303857, 2020). "The antipsychotic clozapine, which at least partly binds to the dopamine receptor D2,can reverse this deficit in schizophrenia." (PMID 32122379, 2020). "Enhancers from schizophrenia GWAS regions were found to interact with the promoters of a number of genes (DRD2, GRIN2A, CACNA1C, and FOXP1), which have previously been unambiguously linked to schizophrenia." (PMID 31963710, 2020). "There is an extensive literature on the importance of DRD2 for the psychopharmacology of both schizophrenia and MDD56,57." (PMID 31797917, 2019). "A recent paper indicated that deletion of Drd2 from PV-positive interneurons resulted in schizophrenia-like phenotypes in mice." (PMID 30604007, 2019).
schizophrenia (continued). "While all the dopamine receptors are important for brain homeostasis, D2 dopamine receptor (Drd2) is closely related with brain disorders including schizophrenia, Parkinson’s disease and drug addiction." (PMID 30604007, 2019). "Of note, the Drd2 expression pattern is distinctive between Drd2 reporter rats and mice in the PFC and hippocampus, two brain regions implicated in the pathophysiology of schizophrenia." (PMID 30604007, 2019). "Here, we discuss the new information revealed by the Drd2 reporter rats and the relevance to physiology and schizophrenia." (PMID 30604007, 2019). "Risperidone (targeting DRD2) is used to treat schizophrenia, bipolar disorder, and irritability in autistic patients." (PMID 31481665, 2019). "MetaCore Gene Ontology Diseases identifies Schizophrenia and nervous system diseases as gene categories most related to gene changes in Drd2 neurons." (PMID 30135420, 2018). "to estimate the prevalence of TaqIA, -141C and rs6280 polymorphisms of theANKK1, DRD2 and DRD3 genes and evaluate their association with theoccurrence of metabolic syndrome in patients with refractory schizophrenia." (PMID 29791666, 2018). "Because this gene plays a relevant role in Schizophrenia, this finding of a more specific DRD2 community will improve the understanding of the genetic factors related with this disorder." (PMID 29304112, 2018). "The DRD2 expression levels in chronic schizophrenia patients were statistically higher than those in controls (t=2.168, p=0.037)." (PMID 29156812, 2017). "We found that the mRNA levels of DRD2 were significantly higher in chronic schizophrenia patients than those in controls, which is consistent with the findings of three studies." (PMID 29156812, 2017). "The gene coding for the dopamine receptor D2 (DRD2), located on chromosome 11q22-2, is one of the most studied marker of susceptibility for schizophrenia." (PMID 28085950, 2017). "Our results showed that DRD2 gene expression levels in PBLs were correlated with the deficit syndrome of chronic schizophrenia patients." (PMID 29156812, 2017). "Considering rs1800497 of the DRD2/ANKK1 locus, impaired selective attention (assessed by Stroop-PI) is associated with schizophrenia more than genetics." (PMID 28085950, 2017). "All currently available drugs to treat schizophrenia are believed to act primarily by blocking Drd2, and to date, effective therapeutic drugs based on other target molecules have not been developed." (PMID 28535798, 2017). "In conclusion, a correlation was observed between increased deficit syndrome severity and elevated DRD2 expression levels in PBLs of chronic schizophrenia patients receiving long-term clozapine treatment." (PMID 29156812, 2017). "In conclusion, a correlation was observed between increased deficit syndrome severity and elevated expression levels of DRD2 in PBLs of chronic schizophrenia patients receiving long-term clozapine treatment." (PMID 29156812, 2017). "The D2 dopamine receptor gene (DRD2) is inconsistently implicated in substance abuse, Alzheimer's disease, schizophrenia, and PTSD." (PMID 27110438, 2016). "Given that the dopamine system may contribute to the risk for schizophrenia, we conducted an update meta-analysis of all eligible published case–control studies to evaluate the effect of C957T, TaqI and Ser311Cys polymorphisms of the DRD2 gene on the overall risk for SZ." (PMID 27829443, 2016). "DRD2 has been identified as a genome wide significant locus for schizophrenia (SCZ), and DRD2 is the primary target of all approved antipsychotic drugs." (PMID 26805891, 2016). "Another study showed that drd2 mRNA levels in lymphocytes of peripheral blood were correlated with positive symptoms in acute schizophrenia patients." (PMID 28096775, 2016).
schizophrenia (continued). "For example, abnormal SPECT findings were found in 41 of 97 AIP affected schizophrenia patients (42%) in a recent study, raising the possibility of coexistence of NS defects combined with DRD2 blockade by antipsychotics." (PMID 25750634, 2015). "Antipsychotics act mainly on the DRD2 in brains of patients with schizophrenia, and provide symptomatic relief, particularly for positive symptoms." (PMID 26694375, 2015). "The DRD2 mRNA level was correlated with symptom severity related to the excited factor of the PANSS in patients with schizophrenia/schizophreniform disorder." (PMID 26561806, 2015). "Based on the connection between dopamine receptor 2 and schizophrenia we focused our analysis on DRD2." (PMID 26290802, 2015). "The Drd2 participates in modulating local motor activity, schizophrenia, and working memory in the prefrontal cortex." (PMID 26793069, 2015). "Genetic evidence for disruption of neuromodulators is so far restricted to dopamine, with a genome-wide significant GWAS signal localized to DRD2 (Schizophrenia Working Group of the Psychiatric Genomics Consortium, 2014)." (PMID 26050040, 2015). "After adjusting for age and PMI, DTNBP1, COMT and DRD2 were found to be differentially methylated between the two schizophrenia subgroups." (PMID 24399042, 2014). "One early study of epigenetics in schizophrenia used lymphocytes of one discordant and one concordant pair of MZ twins to characterize the 5’ regulatory region of the dopamine D2 receptor gene (DRD2) through bisulfite sequencing." (PMID 25484923, 2014). "DRD2 antagonists are prescribed for treating schizophrenia, but these block dopamine signaling in all DRD2 expressing neurons and are associated with adverse side effects, including enhanced appetite and excessive weight gain." (PMID 25183960, 2014). "The APOA-I genes are clustered on chromosome 11q23, which has been a locus of interest in schizophrenia research because it is near the dopamine 2 receptor (DRD2) gene." (PMID 24710015, 2014). "DRD2 mRNA levels in PBLs of drug-naive schizophrenia patients were found to be over-expressed in a microarray analysis." (PMID 24086483, 2013). "Further supporting a strong dopaminergic basis of PL, patients with schizophrenia given DRD2 blocking typical antipsychotics, but not atypical antipsychotics, show significant PL impairment." (PMID 23596404, 2013). "There are few reports about the relevance between DRD2 mRNA levels in PBLs and the psychiatric symptoms of schizophrenia." (PMID 24086483, 2013). "In conclusion, DRD2 mRNA levels in PBLs are correlated with positive symptoms in acute schizophrenia patients, and DAT mRNA levels in PBLs of chronic schizophrenia patients are over-expressed." (PMID 24086483, 2013). "Among these factors, most of attention has been attributed to the dopamine D2 receptor (DRD2) due to its pathological role in schizophrenia." (PMID 19653907, 2009). "Effective known treatments for schizophrenia are those that principally antagonize the DRD2 subtype of dopamine receptor." (PMID 17651483, 2007). "Clozapine and olanzapine are distinct from the other drugs in binding to members of the GABA receptor family, which has been speculated to influence schizophrenia via the GABRA5 receptor through upstream regulation of DRD2." (PMID 40720497, 2025). "Of particular interest, the Srrm2+/− and Dagla+/− mutants had a significant (FDR < 0.05) upregulation of the “response to dopamine” gene set in the striatum, including increased expression of Drd1 and Drd2, which are dopamine receptors highly relevant to schizophrenia." (PMID 41022686, 2025).
schizophrenia (continued). "However, NDMC has no dopaminergic activity and is unable to effectively treat the positive symptoms of schizophrenia by itself; clozapine, with its DRD2 antagonism, also plays an active role in treating schizophrenia." (PMID 40863247, 2025). "In our previous papers, it has been demonstrated that polymorphisms in insulin-induced gene 2 (INSIG2), LEP, FTO, dopamine D2 receptor (DRD2), and 5-HT receptor genes may contribute to the development of metabolic disorders in schizophrenia." (PMID 38540239, 2024). "Although a link between elevated Drd2 expression and schizophrenia-like behavioral abnormalities has been suggested, it remains to be seen whether there is a link between the other dopamine receptor Drd1 and behavior." (PMID 38336912, 2024). "It has been shown that selective DRD2 deletion from the entire PV interneuron population (PVDRD2KO) causes an increase in the excitatory tone and schizophrenia-like phenotypes in mice, including increased locomotor activity, reduced motivation, and cognitive impairment." (PMID 37945756, 2023). "It was shown that the presence of minor DRD2 alleles in both healthy subjects and patients with schizophrenia was associated with worse emotion recognition." (PMID 36699706, 2023). "DRD2 methylation is closely related to children’s psychological trauma and alcohol dependence and is a marker of schizophrenia showed that increased DRD2 promoter methylation is correlated with decreased DRD2 mRNA levels and increased PRL mRNA levels in the pituitary." (PMID 35865960, 2022). "The DA hypothesis of schizophrenia postulates that hyperactivity of DRD2 contributes to positive symptoms of schizophrenia." (PMID 35062349, 2022). "The schizophrenia patients enrolled in our study received haloperidol, a highly effective and widely prescribed classical antipsychotic, which demonstrates the highest risk of AIP due to the “tight” blockade of the DRD2 in the nigrostriatal pathway." (PMID 36551993, 2022). "Thus, the results of the present study suggest a possible relationship between the DRD2-related co-expression network identified and schizophrenia." (PMID 35871219, 2022). "In this article, our data displayed a consistency between HERV-W ENV and DRD2 in schizophrenia." (PMID 35062349, 2022). "Additionally, the level of DRD2 in schizophrenia was higher than in the control in GSE25673 (p < 0.01)." (PMID 35062349, 2022). "DRD1, DRD2, and HTR2A have been implicated as drug targets in schizophrenia." (PMID 36671883, 2022). "The expression of HERV-W ENV was consistent with DRD2 in schizophrenia patients." (PMID 35062349, 2022). "Here we show that DRD2 antagonist attenuated cortical synaptic pruning, which is hypothesized to be beneficial for schizophrenia patients." (PMID 34750364, 2021). "Thioridazine (THD) is a first-generation antipsychotic drug that belongs to the phenothiazines drug family, primarily blocking dopamine receptor 2 (DRD2), mainly used for the treatment of a wide range of psychotic disorders including schizophrenia and psychosis." (PMID 34944601, 2021). "Rs1799732 (-141C Ins/Del) is a functional SNP located in the 5′-promoter region of DRD2, affecting striatal dopamine receptor density and likely associated with schizophrenia, although not all studies confirm this association." (PMID 32565876, 2020). "Accumulating evidence suggests AKT1 and DRD2-AKT-GSK3 signaling involvement in schizophrenia." (PMID 31959776, 2020). "Potentially harmful stimulation of dopamine receptor D2 by dopamine agonists in schizophrenia." (PMID 32499701, 2020). "It is therefore possible that other DRD2 SNPs may have a modifying effect on the clinical course of schizophrenia." (PMID 32565876, 2020). "However, the existing observations would support that FXR1 is one example of a gene for which further investigation of contribution to schizophrenia, DRD2 signaling, and antipsychotics drug responsiveness is warranted." (PMID 30687136, 2018).
schizophrenia (continued). "The dopaminergic hypothesis of schizophrenia (SZ) postulates that positive symptoms of SZ, in particular psychosis, are due to disturbed neurotransmission via the dopamine (DA) receptor D2 (DRD2)." (PMID 30546022, 2018). "This suggests that these potential decreases in DRD2 isoforms (short and long) may contribute to presynaptic or dendritic pathophysiology in schizophrenia." (PMID 28094812, 2017). "In addition, DRD2 mRNA levels in lymphocytes are suggested to correlate with positive symptoms of schizophrenia, whereas lymphocyte DRD2 binding was reduced after treatment with antipsychotic drug loxapine." (PMID 28358316, 2017). "In contrast to our evidence of decreased DRD2, we and others, find increased DRD2S mRNA in DLPFC in schizophrenia, indicating potential region-specific alterations of this receptor splice variant mRNA in schizophrenia." (PMID 28094812, 2017). "The genes for platelet-derived growth factor beta (PDGFB) and PDGFB receptor (PDGFBR) may be important in the pathology of schizophrenia through interacting with the DRD2/DRD4 and NMDA receptors." (PMID 28117656, 2016). "The genetic interactions between mitochondria and schizophrenia may be revealed by the DRD2-NDUFS7 and the FLNA-ARRB2 interactions." (PMID 28117656, 2016). "There is evidence that suggests DRD2 is dysregulated in schizophrenia brains." (PMID 27992436, 2016). "The association between the dopamine D2 receptor (DRD2) gene and schizophrenia has been studied though no conclusive outcomes have been attained." (PMID 27829443, 2016). "Long known to be the key target of antipsychotic drugs, GWAS data now indicate that the DRD2 gene may play a role in schizophrenia." (PMID 25315827, 2015). "There is, however, more support for the idea that DRD2 can be elevated in schizophrenia DLPFC." (PMID 23720610, 2013). "But most of the later studies failed to support the argument that Cys311 allele of DRD2 poses a genetic risk factor for schizophrenia." (PMID 17651483, 2007). "Thus, we hypothesize that the behavioral abnormalities reminiscent of schizophrenia observed in our mouse model are related to changes in Drd2 expression." (PMID 38336912, 2024). "For example, multiple glutamatergic genes, as well as DRD2 (dopamine D2 receptor) were significant drivers at the CTP-11 meta-locus, in which genes reducing cognitive test performance are strongly associated with risk for schizophrenia (as well as many other forms of psychopathology)." (PMID 36369282, 2022). "However, the status of the serum of DRD2 mRNA expression in schizophrenia is controversial." (PMID 35062349, 2022). "The dopamine hypothesis, the current leading theory of the pathogenesis of schizophrenia, is supported by genetic studies indicating that single nucleotide variations (SNVs) related to dopaminergic transmission, such as DRD2, COMT, DISC1, and PCLO, are associated with a higher risk of schizophrenia." (PMID 34063598, 2021). "In addition, association have been found between DRD2 and DRD4 polymorphisms and novelty seeking, substance abuse and impulsivity behavior, as well as schizophrenia and mood disorders." (PMID 28054193, 2018). "This classical DA hypothesis of schizophrenia was mostly concerned with the hyperactivity of DA signaling in subcortical regions such as striatum, and with significant role of DRD2 in the development of positive symptoms." (PMID 28358316, 2017). "By targeting the gene DRD2, Dopamine may be used for schizophrenia." (PMID 29212201, 2017). "Previous research has indicated that variation in genes encoding catechol‐O‐methyltransferase (COMT) and dopamine receptor D2 (DRD2) may influence cognitive function and that this may confer vulnerability to the development of mental health disorders such as schizophrenia." (PMID 28523234, 2017). "However, more studies are necessary to establish whether changes in drd2 mRNA expression levels could represent a molecular marker for neurodevelopmental changes related to schizophrenia." (PMID 28096775, 2016).